CD274 (CD274 molecule)
Diseases named in the same sentence as CD274 in open-access papers (continued):
Sharing a sentence is not in itself a finding about the gene and the disease.
ulcerative colitis (14 papers, 2016 to 2025). An inflammatory bowel disease involving the mucosal surface of the large intestine and rectum. "Nevertheless, the CD274 (PD-L1) gene probe (227458_at) was identified, with an adjusted p value of 1.73 × 109, and was associated with active ulcerative colitis." (PMID 36011133, 2022). "In addition, we have also published data analysis-based studies on celiac disease in which we highlighted the importance of the B and T lymphocyte associated (BTLA) gene, and programmed cell death 1 ligand 1 (CD274 antigen) in ulcerative colitis." (PMID 39194989, 2024).
co-infection (13 papers, 2015 to 2025). "Recently, it was shown that PRRSV infection alone or co-infection with porcine circovirus type 2 (PCV2) can significantly upregulate surface expression of PD-L1 (CD274) on porcine monocytes-derived dendritic cells (MoDCs)." (PMID 32731586, 2020).
rectal adenocarcinoma (13 papers, 2018 to 2025). "In rectal adenocarcinoma, chromothripsis on chromosome 9 results in the deletion and low expression of CD274 and PDCD1LG2 genes, which may play important roles in the poor response to immunotherapy." (PMID 36761982, 2023).
alopecia (12 papers, 2016 to 2026). Hair loss usually from the scalp. "Consistent with the role of CD274 in the immune tolerance of healthy tissues, treatment with anti-PD-1/PD-L1 antibody for various malignancies results in serious side effects such as gastrointestinal toxicity, skin rashes, and alopecia, as well as kidney, liver, and lung injury." (PMID 35626630, 2022).
Hashimoto thyroiditis (12 papers, 2016 to 2025). An autoimmune disorder caused by the production of autoantibodies against thyroid tissue. "CD274 mutation/deletion was significantly associated with advanced age, Hashimoto’s thyroiditis and increased erythrocyte sedimentation rate." (PMID 34021249, 2021). "Both CD274 and TNFRSF14 genetic changes were significantly associated with Hashimoto’s thyroiditis (p = 0.01, p = 0.04, respectively), and CD274 mutation/deletion additionally associated with increased erythrocyte sedimentation rate (p = 0.0001)." (PMID 34021249, 2021).
ovarian clear cell cancer (12 papers, 2018 to 2025). An invasive malignant neoplasm that arises from the ovary and is characterized by a predominance of clear and hobnail malignant epithelial cells. "Notably, ARID1A mutations, prevalent in > 50% of clear cell ovarian cancers, correlate with increased PD-L1 expression due to direct repression of CD274 gene transcription or heightened mutation loads." (PMID 41029427, 2025).
allergic asthma (11 papers, 2017 to 2025). A asthma with a basis in a pathological type I hypersensitivity reaction. "More recently, studies reported that CD101+CD274+ eosinophils were induced in the blood of patients with eosinophilic esophagitis and allergic asthma, and their levels were positively associated with disease severity." (PMID 32855977, 2020).
latent infection (11 papers, 2017 to 2025). "Additionally, The upregulation of CD274 may contribute to the progression from latent infection to ATB by inhibiting T-cell proliferation." (PMID 40607433, 2025).
tongue squamous cell carcinoma (10 papers, 2020 to 2025). A squamous cell carcinoma that arises from the tongue. "Cancer therapy targeting programmed death receptor-1 (PD-1 or CD279) or programmed death-ligand 1 (PD-L1 or CD274) gives hope to Tongue Squamous Cell Carcinoma (TSCC) treatment." (PMID 35164673, 2022).
anal squamous cell carcinoma (9 papers, 2019 to 2024). A squamous cell carcinoma (SCC) arising from the anal canal or the anal margin (perianal skin). "However, it is notable that loss of STAT1, JAK2, and CD274 was detected in a patient with HPV18-positive anal squamous cell carcinoma who did not benefit from treatment." (PMID 34446728, 2021).
NK/T cell lymphoma (9 papers, 2020 to 2024). "In NK/T cell lymphoma, LMP1 upregulates CD274 (PD-L1) via the NF-κB axis, which agreed with our results of enriched CD274 and NF-κB signalling in the plaque stage." (PMID 39682136, 2024).
septic shock (9 papers, 2011 to 2024). Shock caused by infection; frequently caused by gram negative bacteria, although some cases have been caused by other bacteria, viruses, fungi, and protozoa; characterized by fever, chills, tachycardia, tachypnea, and hypotension. "Whereas PD1 expression on T cells was not a reliable “danger signal” for immune suppression in septic patients, monocytic PD-L1/CD274 intensity was an independent predictor of 28-day mortality in septic shock patients." (PMID 33066260, 2020).
human papillomavirus infection (8 papers, 2020 to 2025). "CD274 acts to block T-cell activation and modulates the pro-inflammatory cytokine production, resulting in the suppression of cellular responses that clear the persistent human papillomavirus infection in cervical tissue." (PMID 34666676, 2021).
asthenia (7 papers, 2020 to 2025). Clinical sign or symptom manifested as debility, or lack or loss of strength and energy. "Coded by the CD274 gene, PD-L1 is the transmembrane protein that can conduce to immunosuppression by combining with PD-1 presented on T cells and eliciting T-cell asthenia." (PMID 36335094, 2022).
acute pancreatitis (6 papers, 2020 to 2024). An acute inflammatory process that leads to necrosis of the pancreatic parenchyma. "An increased frequency of PD-L1/CD274-expressing monocytes is an independent risk factor for infectious complications in acute pancreatitis." (PMID 33066260, 2020).
allergic rhinitis (6 papers, 2020 to 2024). Inflammation of the nasal mucous membranes caused by an IgE-mediated response to external allergens. "In addition, a positive correlation between TNSS and the counts of blood and nasal CD101+CD274+ eosinophils was observed in subjects with allergic rhinitis." (PMID 32855977, 2020). "Besides, KLF4 regulates immune response-related genes including IL1RL1, CD274, and CD44 in human nasal epithelial cells of allergic rhinitis." (PMID 38245772, 2024).
dementia (6 papers, 2019 to 2024). Loss of intellectual abilities interfering with an individual's social and occupational functions. "The phenotypic transformation from homeostatic microglia towards reactive microglia in dementia pathologies is associated with TREM2, HLA-DRA, ENTPD1 (CD39), CD80 (B7-1), CD86 (B7-2), CCR5, CD274, ITGAX (CD11c), TIMD4 and MRC1." (PMID 33113879, 2020).
endotoxemia (6 papers, 2013 to 2025). "Finally, we identified and verified 9 key genes (Cd274, Cxcl1, Cxcl9, Icam1, Ifit2, Isg15, Stat1, Tlr2, and Usp18), and we predicted seven potential drugs for multi-organ damage in LPS-induced endotoxemia." (PMID 33330617, 2020). "In endotoxemia, NK-κB and C5a induced Cd274 expression to promote immune suppression, which may indirectly increase the uncontrolled inflammation." (PMID 33330617, 2020).
MALT lymphoma (6 papers, 2019 to 2025). An indolent, extranodal type of non-Hodgkin lymphoma composed of small B-lymphocytes (centrocyte-like cells). "CD274 (PD-L1) inactivation by mutation/deletion is highly restricted to thyroid MALT lymphoma, and rarely seen in MALT lymphoma of other sites or SMZL." (PMID 34021249, 2021). "Among MALT lymphoma of various sites, the most prominent findings were frequent CD274 (52.6%), TNFRSF14 (52.6%), TET2 (85.5%) and TNFAIP3 (30%) mutations in the thyroid cases." (PMID 34021249, 2021).
ovarian serous cystadenocarcinoma (6 papers, 2022 to 2025). A malignant serous cystic epithelial neoplasm arising from the ovary. "Positive correlations have been found between the gene expression of integrin αV (ITGAV) and PD-L1 (CD274) or CD44 in ovarian serous cystadenocarcinoma from the OncoDB online database." (PMID 40093794, 2025). "Positive correlations were found between the mRNA levels of BCL3 with some of these target genes, such as TNFAIP3/A20, CCL2, CD274, and CXCL10, in brain lower grade glioma (LGG) and ovarian serous cystadenocarcinoma (OV) samples from TCGA database." (PMID 35990614, 2022).
ductal carcinoma (5 papers, 2019 to 2025). "The tumoral expression of CD274, TNFAIP3, IFNG and IDO1 in biopsy of breast ductal carcinoma was confirmed at the protein level via immunohistochemistry imaging." (PMID 38201582, 2023). "At the protein level, via immunohistochemistry, a weak expression of CD274 and moderate expression of ferroptosis drivers (IFNG, TNFAIP3 and IDO1) were observed in biopsy of ductal breast carcinoma." (PMID 38201582, 2023).
neurofibroma (5 papers, 2016 to 2024). An intraneural or extraneural neoplasm arising from nerve tissues and neural sheaths. "Notably, we identified tumor-associated IDO1+/CD274+ (PD-L1)+ dendritic cells, which represent the first such observation in any NF1 animal model and suggest the role of the upregulation of immune checkpoints in mature neurofibromas." (PMID 37817770, 2023).
osteoporosis (5 papers, 2020 to 2025). A condition of reduced bone mass, with decreased cortical thickness and a decrease in the number and size of the trabeculae of cancellous bone (but normal chemical composition), resulting in increased fracture incidence. "Interestingly, our research group has found a significantly reduced expression of CD274 on hBMSCs from osteoporosis patients in comparison with hBMSCs from sex‐ and age‐matched control donors (n = 7 per group)." (PMID 35088539, 2022).
brucellosis (4 papers, 2022 to 2026). Brucellosis is a bacterial infection that spreads from animals to people via unpasteurized dairy products or by exposure to contaminated animal products or infected animals. "The team also found that expression of CD274/PDL1, LAG3, and Ly6E (the putative human homolog of Sca-1) was upregulated in the whole blood of acute brucellosis patients." (PMID 41583483, 2025).
mucinous ovarian cancer (4 papers, 2022 to 2025). An invasive malignant neoplasm that arises from the ovary and is characterized by the presence of malignant epithelial cells that contain intracytoplasmic mucin and may resemble the epithelial cells of the endocervix or gastrointestinal tract. "In mucinous ovarian cancer, the majority of tumours were described as immune cold, characterised by the absence of T cells and CD274+ cells." (PMID 39966658, 2025).
mycosis fungoides (3 papers, 2020 to 2025). Classical mycosis fungoides is the most common type of mycosis fungoides (MF), a form of cutaneous T-cell lymphoma, and is characterized by slow progression from patches to more infiltrated plaques and eventually to tumors. "SVs involving CD274 are also documented in mycosis fungoides with large cell transformation, with small numbers of patients demonstrating high rates of disease response, though these responses appeared to be ephemeral." (PMID 41295262, 2025).
polycystic ovary syndrome (3 papers, 2021 to 2025). A disorder that manifests as multiple cysts on the ovaries. "This study is to investigate the relationship of programmed cell death 1 (PD-1; also known as PDCD1) and programmed death-1-ligand 1 (PD-L1; also known as CD274) single nucleotide polymorphisms (SNPs) with polycystic ovary syndrome (PCOS)." (PMID 33521133, 2021).
rhinitis (3 papers, 2014 to 2023). An inflammation of the mucous membrane lining the nose, usually associated with nasal discharge. "We found that most of the immune- and cytokine-related signatures were significantly altered between AR1 and AR2, revealing a gradual increase in the expression of top genes and rhinitis marker genes (e.g., IL1RL1, CD274, and CD44) from healthy controls to AR1 and then AR2." (PMID 37206297, 2023).
Airway obstruction (2 papers, 2022 to 2024). Obstruction of conducting airways of the lung. "In a murine model, intraperitoneal IL-18 injection increased eosinophil recruitment into the airways, and intranasal rIL-18 administration also transformed CD274-eosinophils to CD274+ pathogenic eosinophils that were shown to promote mucus hypersecretion and airway obstruction." (PMID 39554494, 2024).
gout (2 papers, 2022 to 2025). A condition characterized by painful swelling of the joints, which is caused by deposition of urate crystals. "PTGS2, CASP8, NFE2L2, and CD274 were identified as key pyroptosis-related genes associated with gout." (PMID 36291136, 2022). "Experimental validation revealed that PTGS2 and NFE2L2 were significantly upregulated, and CASP8 and CD274 were significantly downregulated in gout." (PMID 36291136, 2022). "miR-16-5p, miR-128-3p, miR-20a-5p, and miR-155-5p can potentially influence pyroptosis and the occurrence and development of gout by affecting the expression of the PTGS2, CASP8, NFE2L2, and CD274 genes." (PMID 36291136, 2022).
iron deficiency (2 papers, 2020 to 2024). "The effects of iron deficiency by DFO on the EMT and immune checkpoints were assessed by measuring the mRNA levels of CDH2 and CD274, respectively." (PMID 33302911, 2020).
Klebsiella Infections (2 papers, 2013 to 2024). Infections with bacteria of the genus KLEBSIELLA. "Additionally, analysis of the inhibitory molecule CD274 on lung DC during Klebsiella infection revealed a massive upregulation on CD11b DC and MoDC and to a lesser extent on CD103 DC suggesting another pathway of Klebsiella pneumonia-mediated suppression." (PMID 24044871, 2013).
MALT lymphomas of the thyroid (2 papers, 2021). "The present study shows for the first time frequent CD274 (PD-L1) inactivation by mutation and deletion in a human tumour, i.e. thyroid MALT lymphoma." (PMID 34021249, 2021). "Most CD274 mutations in thyroid MALT lymphoma were likely deleterious." (PMID 34021249, 2021). "In addition, deletion of CD274 (PD-L1) are frequently found in MALT lymphomas of the thyroid, together with mutation in up to 68% of cases (see later)." (PMID 35008340, 2021). "Taken together, 68% of thyroid MALT lymphomas had CD274 mutation or deletion or both." (PMID 34021249, 2021). "We found frequent deleterious mutations of TET2 (86%), CD274 (53%), TNFRSF14 (53%), and TNFAIP3 (30%) in thyroid MALT lymphoma." (PMID 34021249, 2021). "We correlated TET2, TNFRSF14, CD274 and TNFAIP3 mutation AAF in thyroid MALT lymphoma in order to understand the sequence of their occurrence." (PMID 34021249, 2021). "Taken together, inactivation of both CD274 (PD-L1) and TNFRSF14 in thyroid MALT lymphoma most likely abolishes their negative regulation to T-helper cells, hence enhances their function, leading to exaggerated T-cell help to support malignant B-cells." (PMID 34021249, 2021). "There is no detectable PD-L1 expression by immunohistochemistry in thyroid MALT lymphoma, irrespective of CD274 genetic changes." (PMID 34021249, 2021).
mastitis (2 papers, 2021 to 2024). Inflammation of breast tissue during lactation or postpartum due to an obstructed duct or infection. "Of note, CD14pos monocytes expressing CD274 accumulate in blood of cattle infected by Mycoplasma bovis, a strongly immunosuppressive pathogen causing antibiotic resistant mastitis ant other diseases." (PMID 33717136, 2021).
scrub typhus (2 papers, 2021 to 2026). Scrub typhus is a rare dust mite-borne infectious disease caused by the Orientia tsutsugamushi bacterium and characterized clinically by an eruptive fever which is potentially serious. "In contrast, the expression of a co-inhibitory marker, indicated by CD274, was higher in both pDCs and cDCs of scrub typhus patients than in those of HCs, in agreement with several studies on HIV and HCV infections." (PMID 34276693, 2021). "After reproducing the pro-inflammatory milieu using a cytokine cocktail including IFN-γ, IL-12, and TNF-α, we observed the dynamics of CD86 and CD274 expression patterns in pDCs and cDCs, which was similar to our data in scrub typhus patients." (PMID 34276693, 2021). "The percentages of CD274+ cDCs were significantly higher in scrub typhus patients than in the HCs (median 17.0% versus 2.9%, P = 0.006)." (PMID 34276693, 2021). "The percentages of both CD86+ and CD274+ pDCs were significantly higher in scrub typhus patients compared to the HCs (for CD86+ pDCs, median 39.9% versus 11.3%, P = 0.031; and for CD274+ pDCs, 13.6% versus 0.2%, P = 0.001)." (PMID 34276693, 2021).
female infertility (1 paper, 2024). Diminished or absent ability of a female to achieve conception. "It would be interesting for us to further illuminate the deeper mechanism underlying the function of IL6R, CD274 and CASR, and also HA/NA PCOS classification markers on the formation of PCOS and female infertility." (PMID 38347589, 2024). "Also from the knowledge graph, we noticed the important role for our newly discovered HA and NA PCOS functional markers IL6R, CD274 and CASR on female infertility." (PMID 38347589, 2024).
hemochromatosis (1 paper, 2018). A disorder of iron metabolism characterized by a triad of HEMOSIDEROSIS; LIVER CIRRHOSIS; and DIABETES MELLITUS. "Subsequent validation using quantitative polymerase chain reaction confirmed the differential involvement of two cell adhesion molecules HFE (hemochromatosis) and CD274 and their related molecules in the acute phase event." (PMID 29642405, 2018).
Lassa fever (1 paper, 2025). A viral hemorrhagic fever that is caused by the Lassa virus, which is transmitted by contact with infected rodents; it is characterized by fever, headache, malaise, myalgia, and hearing loss. "We also describe, for the first time, the expansion of MDSCs (predominantly of the granulocytic lineage) during fatal Lassa fever in the blood and their expression of CD279 and CD274." (PMID 40245043, 2025).